DNAJC12 (DnaJ heat shock protein family (Hsp40) member C12)
Description:
Probable co-chaperone that participates in the proper folding of biopterin-dependent aromatic amino acid hydroxylases, which include phenylalanine-4-hydroxylase (PAH), tyrosine 3-monooxygenase (TH) and peripheral and neuronal tryptophan hydroxylases (TPH1 and TPH2).
Synonyms: JDP1; HPANBH4
Tractability: No criterion of Open Targets' tractability assessment is met for any kind of drug.
Gene: Protein-coding gene on chromosome 10 (67,796,668 to 67,838,188, reverse strand). Ensembl gene ENSG00000108176.
Subcellular location: Cytoplasm (Isoform a)
Gene Ontology:
Molecular function: protein binding
Cellular component: cytoplasm
Genetic constraint (gnomAD): Loss-of-function variants: 21 observed, 25.35 expected, observed/expected ratio (o/e) 0.83, 90% interval 0.59 to 1.19. The upper end of that interval is the gene's LOEUF score, 1.19, which puts it in group 5 of 6, group 1 being the genes least tolerant of losing a copy. Missense variants: 201 observed, 213.25 expected, observed/expected ratio (o/e) 0.94, 90% interval 0.84 to 1.06. Synonymous variants: 67 observed, 72.46 expected, observed/expected ratio (o/e) 0.92, 90% interval 0.76 to 1.13.
Gene-disease validity (ClinGen):
ClinGen rates the evidence that DNAJC12 causes each of these diseases.
hyperphenylalaninemia due to DNAJC12 deficiency (autosomal recessive): Definitive. Mild non-BH4-deficient hyperphenylalaninemia (HPANBH4) is an autosomal recessive disorder characterized by increased serum phenylalanine usually detected by newborn screening and associated with highly variable neurologic defects, including movement abnormalities and intellectual disability.
Homologues: Orthologues: chimpanzee DNAJC12 (97% identical), pig DNAJC12 (86% identical), dog DNAJC12 (85% identical), macaque DNAJC12 (83% identical), rabbit DNAJC12 (82% identical), guinea pig DNAJC12 (80% identical), mouse Dnajc12 (77% identical), rat Dnajc12 (69% identical), tropical clawed frog dnajc12 (54% identical), zebrafish dnajc12 (49% identical), Drosophila melanogaster l(3)80Fg (21% identical), Caenorhabditis elegans dnj-8 (19% identical), and 9 more. Paralogues in human: DNAJC10 (25% identical), DNAJC16 (25% identical), DNAJC11 (24% identical), DNAJC17 (21% identical), DNAJC21 (21% identical), DNAJC13 (20% identical), DNAJC5 (20% identical), DNAJC2 (20% identical), DNAJC1 (19% identical), DNAJC5B (19% identical), DNAJC25 (18% identical), DNAJC18 (18% identical), and 8 more.
Diseases named in the same sentence as DNAJC12 in open-access papers:
DNAJC12 is named in the same sentence as 35 diseases in open-access papers, as found by Europe PMC text mining. Sharing a sentence is not in itself a finding about the gene and the disease. The quoted sentences say what the papers report.
Hyperphenylalaninemia (12 papers, 2017 to 2025). "Based on previous case reports and the findings from this study, the clinical symptoms associated with DNAJC12 gene mutations show similarities to other forms of hyperphenylalaninemia." (PMID 39923104, 2025). "This study aims to elucidate the role of DNAJC12 in intellectual disability and explore the mechanisms by which DNAJC12 deficiency leads to hyperphenylalaninemia through developing a DNAJC12 gene knockout mouse model." (PMID 39923104, 2025). "Recently, several pathogenic variants of DNAJC12 have been reported, associated with hyperphenylalaninemia and parkinsonism." (PMID 40113792, 2025). "DNAJC12-deficient hyperphenylalaninemia is a newly described, autosomal recessively inherited neurotransmitter synthesis disorder, and biallelic pathogenic variants of DNAJC12 have been identified in all patients." (PMID 38248634, 2024). "DNAJC12-deficient hyperphenylalaninemia is a recently described inborn error of metabolism associated with hyperphenylalaninemia, neurotransmitter deficiency, and developmental delay caused by biallelic pathogenic variants of the DNAJC12 gene." (PMID 38248634, 2024). "DNAJC12 deficiency is a recently described inherited metabolic disorder resulting in hyperphenylalaninemia and neurotransmitter deficiency." (PMID 39584997, 2024). "Bi-allelic mutations of DNAJC12 have been associated with hyperphenylalaninemia and neurodevelopmental delay in children." (PMID 35077669, 2022). "Recently hyperphenylalaninemia (HPA) caused by variants in DNAJC12 was reported and this suggested a new strategy for diagnosis." (PMID 32519510, 2020). "However, there are also some differences between patients with DNAJC12 gene mutations and those with other types of hyperphenylalaninemia." (PMID 39923104, 2025). "Moreover, variants in DNAJC12 cause a neurometabolic disorder, now defined as DNAJC12 deficiency, that manifests as hyperphenylalaninemia, accompanied by dopamine (DA) and serotonin depletion and parkinsonism, revealing reduced levels of functional AAAHs." (PMID 40113792, 2025). "Patients with congenital DNAJC12 deficiency present monoamine neurotransmitter decline and heterogenous clinical spectrum, including hyperphenylalaninemia and parkinsonism of varying severity, spanning from L-Dopa-responsive dystonia to severe neurodevelopmental delay and intellectual disability." (PMID 40113792, 2025). "Building upon existing clinical and experimental research, our hypothesis posits that DNAJC12 mutations result in diminished activity of aromatic amino hydroxylases, leading to hyperphenylalaninemia and reduced neurotransmitter levels, which consequently contribute to intellectual disability." (PMID 39923104, 2025). "WES analysis has shown that neither of these patients had pathogenic, likely pathogenic, or variants of uncertain significance (VUS) above 50% posterior probability in genes associated with hyperphenylalaninemia (GCH1, PCBD1, PTS, QDPR, SPR and DNAJC12)." (PMID 40473815, 2025). "To elucidate the role of DNAJC12 in intellectual disability and explore the mechanisms by which DNAJC12 defficiency leads to hyperphenylalaninemia, we have constructed the first DNAJC12 gene knockout mouse model and conducted corresponding experiments." (PMID 39923104, 2025). "DNAJC12 has been described to regulate the stability of PAH and mutations in its gene cause hyperphenylalaninemia and neurological symptoms in patients." (PMID 39695187, 2024). "Since the time of the patient’s initial testing, the DNAJC12 gene has been added to this panel; however, it is unclear if all babies with hyperphenylalaninemia undergo comprehensive molecular studies or even have access to this testing." (PMID 38248634, 2024). "Hyperphenylalaninemia (HPA) comprises a group of genetically heterogeneous disorders, including deficiencies in PAH, tetrahydrobiopterin (BH4), and DNAJC12, which are associated with six genes (PAH, PTS, GCH1, QDPR, PCBD1, and DNAJC12)." (PMID 28982351, 2017).
Hyperphenylalaninemia (continued). "Here, we review the management of DNAJC12-related hyperphenylalaninemia and compare our patient to other reported cases in the literature to investigate how early detection and management may impact clinical outcomes." (PMID 38248634, 2024). "Protein-folding diseases are related to chaperone defects such as DNAJC12 and DNAJC6, involved in neurotransmitter disturbances and a spectrum of symptoms including early Parkinsonism (and hyperphenylalaninemia in the case of DNAJC12)." (PMID 30014209, 2018).
Parkinsonism (9 papers, 2018 to 2025). Characteristic neurologic anomaly resulting from degeneration of dopamine-generating cells in the substantia nigra, a region of the midbrain, characterized clinically by shaking, rigidity, slowness of movement and difficulty with walking and gait. "Pathogenic variants of the J-domain protein DNAJC12 cause parkinsonism, which is associated with a defective interaction of DNAJC12 with tyrosine hydroxylase (TH), the rate-limiting enzyme in dopamine biosynthesis." (PMID 40113792, 2025). "This animal model will be useful to study the mechanisms causing HPA, parkinsonism and intellectual disabilities and to test novel therapeutic options in patients with DNAJC12 mutations." (PMID 39695187, 2024). "Given that Parkinsonism due to DNAJC12-deficiency is dopa-responsive, supplementation with levodopa/carbidopa is an established therapeutic to both treat and potentially prevent this manifestation." (PMID 38248634, 2024). "In studies of unrelated families, mutations of DNAJC12 have been associated with early-onset parkinsonism, dystonia and intellectual disability." (PMID 32811487, 2020). "Mutation of the DNAJC12 gene is typically associated with non-progressive Parkinsonism, but is also detectable in breast carcinoma where its contribution and mechanisms are unexplored." (PMID 33718139, 2021). "Recently, biallelic mutations in the DNAJC12 gene, coding for a heat shock co-chaperone of the HSP40 family, have been identified in individuals with mild HPA and a broad spectrum of clinical symptoms including dystonia, speech delay, axial and limb hypertonia, parkinsonism and psychiatric features." (PMID 32456656, 2020).
Dystonia (6 papers, 2020 to 2025). An abnormally increased muscular tone that causes fixed abnormal postures. "Patients with DNAJC12 gene mutations also presented elevated blood phenylalanine concentrations, and untreated patients may have intellectual problems, muscle dystonia abnormalities, and psychiatric-behavioral problems." (PMID 39923104, 2025).
developmental delay (4 papers, 2021 to 2024). "When patients with p.R53H have persistently high Phe levels and exhibit neurological symptoms, such as developmental delay and behavioral disorder, DNAJC12 deficiency should be considered for differential diagnosis." (PMID 33803550, 2021).
phenylketonuria (4 papers, 2017 to 2023). Phenylketonuria (PKU) is the most common inborn error of amino acid metabolism and is characterized by mild to severe mental disability in untreated patients. "In contrast, in samples of patients with phenylketonuria, these metabolites were normal and DNAJC12 deficiency and dihydropteridine reductase deficiency can also rank fourth or fifth." (PMID 32024143, 2020). "We included three IEM, all characterized by an increase of phenylalanine: phenylketonuria, dihydropteridine reductase deficiency, and DNAJC12 deficiency." (PMID 32024143, 2020). "We would like to emphasise that DNAJC12 should be considered as a differential diagnosis for HPA after excluding PAH deficiency, phenylketonuria and HB4 disorder metabolism." (PMID 37799141, 2023).
breast carcinoma (3 papers, 2018 to 2024). "A critical role for DnaJ heat shock protein family (Hsp40) member C12 (DNAJC12) in breast cancer chemotherapy resistance was identified, as DNAJC12 was shown to suppress both DOX-induced ferroptosis and apoptosis, contributing to treatment resistance." (PMID 39867656, 2024). "In summary, we have determined that ESR1 and ERBB4 are upstream and downstream genes, respectively, of DNAJC12 in breast carcinoma." (PMID 33718139, 2021). "Currently, DNAJC12 has been seldom researched in breast carcinoma, and the relation between DNAJC12 and ESR1 is still unclear." (PMID 33718139, 2021). "ESR1 is positively correlated with DNAJC12 and ERBB4, and DNAJC12 is positively correlated with ERBB4 in breast carcinoma." (PMID 33718139, 2021). "The mRNA expression level of DNAJC12 is generally higher in breast carcinoma, especially in ESR1-positive breast carcinoma tissues." (PMID 33718139, 2021). "ESR1 positively correlates with DNAJC12 and ERBB4, and DNAJC12 also positively correlates with ERBB4 in breast carcinoma." (PMID 33718139, 2021). "All signs point to the conclusion that ESR1 acts upstream of DNAJC12 to enhance DNAJC12 expression in breast carcinoma." (PMID 33718139, 2021). "The DNAJ family of proteins are considered regulators of CSC function, and DNAJC12 transcript expression was found to be upregulated in breast CSCs compared to adherent breast cancer cells." (PMID 30100995, 2018). "The cBioPortal tool was employed to analyze the TCGA database for correlativity among the expression of ESR1, DNAJC12, and ERBB4 in breast carcinoma." (PMID 33718139, 2021). "A new problem was arisen whether there are genes in common that correlate with ESR1, DNAJC12, and ERBB4 expression in breast carcinoma, the cBioPortal tool was first used to output the lists containing genes related to ESR1, DNAJC12, or ERBB4." (PMID 33718139, 2021).
gastric cancer (3 papers, 2019 to 2022). A primary or metastatic malignant neoplasm involving the stomach. "In addition, DNAJ member c12 (DnaJC12) is associated with the aggressive phenotype of gastric cancer." (PMID 31878360, 2019). "The transcriptome analysis has identified that the increased expression of DnaJC12 is correlated with lymphatic invasion, infiltrative growth type, lymph node metastasis, and progression of gastric cancer." (PMID 31878360, 2019).
lung carcinoma (2 papers, 2021 to 2022). "Moreover, in lung cancer, DNAJC12 levels are upregulated, while DNAJC12 knockdown reduces the malignant properties and tumor growth of lung cancer cells in vitro and in vivo by inhibiting activation of β-catenin." (PMID 34948322, 2021).
attention deficit-hyperactivity disorder (1 paper, 2024). A disorder characterized by a marked pattern of inattention and/or hyperactivity-impulsivity that is inconsistent with developmental level and clearly interferes with functioning in at least two settings (e.g. at home and at school). "Speech delay and behavioral issues such as ASD and Attention Deficit Hyperactivity Disorder have been described in multiple DNAJC12 deficiency patients in the literature." (PMID 39584997, 2024).
breast tumors (1 paper, 2024). "The expression of the JDP1 (DNAJC12) gene was directly associated with the ER transactivation activity in breast tumors, and also upregulated in ER+ cultures of BCSCs." (PMID 38255948, 2024).
Cirrhosis (1 paper, 2025). A chronic disorder of the liver in which liver tissue becomes scarred and is partially replaced by regenerative nodules and fibrotic tissue resulting in loss of liver function. "Moreover, DNAJC12, a heat shock protein, was associated to ER stress, but has not been associated to NAFLD, cirrhosis, or metabolic disease yet." (PMID 40489530, 2025).
cognitive deficits (1 paper, 2025). "Traditionally, DNAJC12 has been regarded as a chaperone for AAAHs, with mutations in the DNAJC12 gene leading to reduced AAAHs activity and consequently, cognitive deficits." (PMID 39923104, 2025).
colorectal tumor (1 paper, 2016). "High expression of the HSP40 family member DNAJC12 has been found to correlate with colorectal tumor progression and invasion and with a poor response to neoadjuvant concurrent chemoradiotherapy." (PMID 27144453, 2016).
late-onset Alzheimers disease (1 paper, 2014). This is the most common form of the disease, which happens to people age 65 and older. "Other genes mapping in the deleted region, including DNAJC12 (MIM 606060), HERC4 (MIM 609248), PBLD (MIM 612189), HNRNPH3 (MIM 602324), RUFY2 (MIM 610328), STOX1 (MIM 609397), and CTNNA3 (MIM 607667), have been linked to late-onset Alzheimer’s disease (AD6; MIM 605526)." (PMID 24297458, 2014).
lung squamous cell carcinoma (1 paper, 2019). "In our study, we found that the expression of LINC00668 is associated with A2ML1 and DNAJC12; of which A2ML1 has been shown to be closely related to the treatment of lung squamous cell carcinoma and can be used as a potential prognostic biomarker." (PMID 31850229, 2019).
prostate carcinoma (1 paper, 2021). A carcinoma that arises from epithelial cells of the prostate gland. "In prostate cancer cells, the mRNA expression of DNAJC12 can be also enhanced by AIbZIP (androgen-regulated transcription factor) located in the endoplasmic reticulum, which is relevant to the androgen and endoplasmic reticulum stress." (PMID 33718139, 2021).
cancer (6 papers, 2016 to 2022). A tumor composed of atypical neoplastic, often pleomorphic cells that invade other tissues. "In gastric cancer, increased mRNA expression of DNAJC12 is correlated with cancer invasion, lymph node metastasis, and disease progression, thus having higher morbidity and mortality rates." (PMID 34948322, 2021). "GSEA revealed that genes associated with cancer stem cells (CSC) (e.g., NES, TSPAN8, DPPP, DNAJC12, and MYC) were highly ranked and comprised 70% of the top 25 genes differentially upregulated in the DTX-resistant cells." (PMID 30100995, 2018). "TCF7L1 encodes a TF in the WNT pathway which regulates the expression of cell cycle related genes and is a central regulator of tumor growth and initiation; DNAJC12 is a chaperone upregulated in several cancer types." (PMID 26792175, 2016). "Abnormal expression of DNAJC12 in cancer tissues might be used as a potential marker for the disease." (PMID 32519510, 2020). "DNAJC12, also known as Hsp40, has been implicated in cancer but its role in tumorigenesis is not clearly defined." (PMID 30100995, 2018).
tumor (4 papers, 2014 to 2021). "Interestingly, DNAJC12, a gene strongly upregulated in Luminal A and B tumours, was found to interact with HSPA8 under ERSR." (PMID 29954368, 2018). "Previous studies show that HSP members are implicated in tumorigenesis, including tumor suppressors HLJ1 (DNAJB4), Tid1 (DNAJA3), DNAJC25, radio-resistance factor HDJ2 (DNAJA1) and other tumor-related members such as DNAJB6, DNAJC12, DNAJC1, DNAJC12, DNAJC15." (PMID 24658033, 2014).
DNAJC12 also shares sentences with these, for which no sentence is quoted: Intellectual disability (5 papers); metabolic disease (2); Neurodevelopmental delay (2); 22q11.2 deletion syndrome (1); behavioral disorder (1); colon cancer (1); Cornelia de Lange syndrome (1); DOORS syndrome (1); Down syndrome (1); generalized seizures (1); liver disease (1); neuronal ceroid lipofuscinosis (1); pancreatic cancer (1); prostate tumors (1); rectal cancer (1); renal carcinoma (1); restless legs syndrome (1).